PWWP3A (PWWP domain containing 3A, DNA repair factor)
Description:
Involved in the DNA damage response pathway by contributing to the maintenance of chromatin architecture. Recruited to the vicinity of DNA breaks by TP53BP1 and plays an accessory role to facilitate damage-induced chromatin changes and promoting chromatin relaxation. Required for efficient DNA repair and cell survival following DNA damage.
Synonyms: MUM-1; EXPAND1; MUM1; HSPC211
Tractability: Small molecule: it has a high-quality binding pocket. PROTAC: ubiquitination databases record sites on it.
Gene: Protein-coding gene on chromosome 19 (1,354,293 to 1,378,434, forward strand). Ensembl gene ENSG00000160953.
Subcellular location: Nucleus
Subcellular location (Human Protein Atlas): Cytosol; Nucleoplasm
Gene Ontology:
Molecular function: nucleosome binding; protein binding
Biological process: chromatin organization; DNA repair
Cellular component: nucleoplasm; nucleus
Genetic constraint (gnomAD): Loss-of-function variants: 46 observed, 64.85 expected, observed/expected ratio (o/e) 0.71, 90% interval 0.56 to 0.91. The synonymous counts are far from expectation, so gnomAD's model fits this gene poorly and the ratio says little. Missense variants: 942 observed, 844.81 expected, observed/expected ratio (o/e) 1.12, 90% interval 1.06 to 1.18. Synonymous variants: 428 observed, 348.92 expected, observed/expected ratio (o/e) 1.23, 90% interval 1.13 to 1.33.
Homologues: Orthologues: chimpanzee PWWP3A (93% identical), macaque PWWP3A (88% identical), dog PWWP3A (68% identical), rat Pwwp3a (60% identical), mouse Pwwp3a (60% identical), pig PWWP3A (58% identical), guinea pig PWWP3A (57% identical), tropical clawed frog pwwp3a (33% identical), zebrafish si:dkey-57k2.7 (21% identical). Paralogues in human: PWWP3B (43% identical), PWWP4 (36% identical).
Diseases named in the same sentence as PWWP3A in open-access papers:
PWWP3A is named in the same sentence as 4 diseases in open-access papers, as found by Europe PMC text mining. Sharing a sentence is not in itself a finding about the gene and the disease. The quoted sentences say what the papers report.
neuroepithelial tumor (1 paper, 2025). "In contrast, important CpG sites in the PWWP domain containing 3A, DNA repair factor (PWWP3A, commonly known as MUM1) gene locus for the prediction of MC high-grade neuroepithelial tumor with MN1 alteration (HGNET-MN1) were located in the gene body." (PMID 40481322, 2025).
PWWP3A also shares sentences with these, for which no sentence is quoted: breast carcinoma (1 paper); lymphoma (1); tumor (1).